JPH2 (junctophilin 2)
Diseases named in the same sentence as JPH2 in open-access papers (continued):
Sharing a sentence is not in itself a finding about the gene and the disease.
dilated cardiomyopathy (11 papers, 2014 to 2024). "Less commonly, inherited JPH2 variants can also cause dilated cardiomyopathy (DCM), which causes thinning and enlargement of the left ventricle, as well as potentially lethal arrhythmias." (PMID 38438248, 2024). "Genetic variants in JPH2 cause hypertrophic and dilated cardiomyopathy and in some cases also skeletal muscle myopathy." (PMID 35001666, 2022). "Autosomal-dominant and recessive variants in JPH2 have been linked to hypertrophic and dilated cardiomyopathy, respectively." (PMID 35001666, 2022). "Importantly, dominant mutations in the human JPH2 gene are associated with hypertrophic and dilated cardiomyopathy and constitute a relatively rare cause of congenital cardiomyopathies." (PMID 29208631, 2018). "Moreover, mutations in the human JPH2 gene are associated with hypertrophic and dilated cardiomyopathies; mutations in JPH3 are responsible for the neurodegenerative Huntington's disease-like-2 (HDL2), whereas JPH1 acts as a genetic modifier in Charcot–Marie–Tooth 2K peripheral neuropathy." (PMID 29208631, 2018). "Additionally, mutation in JPH2 can lead to dilated cardiomyopathy." (PMID 28763026, 2017). "Genetic variants in the JPH2 gene can cause hypertrophic cardiomyopathy (HCM) and, in some cases, dilated cardiomyopathy (DCM)." (PMID 38438248, 2024). "On the other hand, in patients with ischemic and dilated cardiomyopathy, calpain-1 expression levels were found to be increased, while JPH2 levels were reduced." (PMID 35001666, 2022). "In isolated mouse cardiomyocytes and myocardial sections from patients with ischemic and dilated cardiomyopathy, the JPH2 distribution was remodeled into irregular punctations and aggregations." (PMID 34050186, 2021). "Decreased levels of Jph2 expression have been reported in animal models of aortic stenosis and hypertrophic and dilated cardiomyopathy." (PMID 29208631, 2018). "There have been some reports of JPH2 downregulation in failing myocytes from a thoracic-aortic banding induced pressure-overload rat model, transgenic mouse models of hypertrophic or dilated cardiomyopathies, and human hypertrophic cardiomyopathy, dilated cardiomyopathy and ischemic cardiomyopathy." (PMID 35069264, 2021). "In 2016, Sabater-Molina showed segregation of the JPH2 p.(Glu85Lys) with dilated cardiomyopathy with or without left ventricular non-compaction cardiomyopathy (LVNC) features in a large family." (PMID 30235249, 2018).
hypertrophic cardiomyopathy (11 papers, 2013 to 2024). "Inherited variants in the JPH2 gene have been shown to cause hypertrophic cardiomyopathy (HCM), a potentially lethal disorder characterized by left ventricular hypertrophy and an elevated risk of cardiac arrhythmias." (PMID 38438248, 2024). "Jph2 deficiency results in acute HF, and Jph2 mutations induce hypertrophic cardiomyopathies and arrhythmias." (PMID 36982963, 2023). "JPH2 is a gene encoding an important protein for intracellular calcium release and contraction, and downregulation of JPH2 has been implicated in patients with hypertrophic cardiomyopathy." (PMID 37293290, 2023). "Previously, missense variants in JPH2 have been linked to hypertrophic cardiomyopathy; however, pathogenic “loss of function” (LOF) variants have not been described." (PMID 31227780, 2019). "Several mutations in human JPH2 have been associated with hypertrophic cardiomyopathy, and can cause a hypertrophyc phenotype when downregulated in mouse cardiac muscle cell lines." (PMID 29208631, 2018). "The G505S (rs140740776) variant in JPH2 was reported to be associated with hypertrophic cardiomyopathy in a relatively small sample of Japanese patients." (PMID 25333069, 2014). "Another JPH2 mutant that is found in other patients with hypertrophic cardiomyopathy, Y141H, also shows hypertrophic skeletal myotubes due to an abnormal junctional membrane complex and increased Orai1-mediated SOCE13." (PMID 33288873, 2020). "Four mutations of the JP2 gene (JPH2), S101R, Y141H, S165F and G505S, have also been identified in patients with HCM (hypertrophic cardiomyopathy)." (PMID 24001019, 2013). "In addition, in human failing heart samples or in patients with hypertrophic cardiomyopathy, the JPH2 levels are markedly reduced." (PMID 29208631, 2018). "Muscle hypetrophy was also observed in mouse skeletal muscle expressing Jph2 with the dominant negative mutations S165F and Y141H, associated with hypertrophic cardiomyopathy in patients." (PMID 29208631, 2018). "We have purified human JP2 (junctophilin-2) and the S101R hypertrophic cardiomyopathy mutant." (PMID 24001019, 2013).
cardiac hypertrophy (5 papers, 2020 to 2025). "In contrast, when [Ca2+]cyt increase dramatically and are maintained, calpain-2 is activated and generates the Jph2 C-terminal fragment (Jph2-CT), which is involved in cardiac hypertrophy." (PMID 40551210, 2025). "Partial silencing of JPH2 expression in HL-1 cells using a small interfering RNA probe targeting murine Jph2 mRNA (shJPH2) resulted in myocyte hypertrophy and increased expression of known markers of cardiac hypertrophy." (PMID 35001666, 2022). "This notion is also supported by previous investigations showing that JPH2-knockout mice develop severe cardiac hypertrophy and that JPH2 could be cleaved by calpain, an intracellular calcium-sensitive protease." (PMID 37446080, 2023). "Given the role of JPH2 in organizing the local t-tubule membranes, the RyR ‘fray zones’ may also represent the primary foci for the t-tubule remodelling observed in cardiac hypertrophy and myopathies." (PMID 36189802, 2022).
atrial fibrillation (4 papers, 2019 to 2023). A disorder characterized by an electrocardiographic finding of a supraventricular arrhythmia characterized by the replacement of consistent P waves by rapid oscillations or fibrillatory waves that vary in size, shape and timing and are accompanied by an irregular ventricular response. "Because decreased JPH2 is reportedly associated with atrial fibrillation and arrhythmias, consistent with CYP-induced cardiotoxicity events, CYP-induced cardiac electrical and mechanical alterations may be closely related to the downregulation of JPH2 in this study." (PMID 34820430, 2021).
Hypertension (4 papers, 2019 to 2024). The presence of chronic increased pressure in the systemic arterial system. "Mendelian randomization utilizing two identified variants (rs17677724 and rs1014754) suggested that a genetically induced decrease in heart FBN2 expression and an increase in adrenal gland JPH2 expression were causally linked to hypertension." (PMID 39011893, 2024). "On the other hand, rs1014754, influencing JPH2 expression positively in the adrenal gland (β = 0.552, P value = 3.47 × 10−8), similarly demonstrated the effect allele's (‘T’) positive association with hypertension (β = 0.0225, P value = 4.8 × 10−5)." (PMID 39011893, 2024). "Reduced expression of JPH2 in arterial smooth muscle cells may cause arterial hypercontractility, contributing to arterial dysfunction, such as hypertension." (PMID 37744379, 2023). "Our findings predict that loss-of-function mutations or decreased expression of JPH2 in vascular SMCs would result in excessive arterial contractility and vascular resistance, potentially contributing to systemic hypertension, ischemic stroke, and vascular cognitive impairment and dementia." (PMID 31591206, 2019). "This study identified novel loci associated with hypertension, including FBN2 and JPH2." (PMID 39011893, 2024). "Thus, our data suggest that hypertension compromises the capacity of junctophilin-2 to anchor the SR to the plasma membrane." (PMID 37549299, 2023). "Additionally, our findings highlight the link between increased JPH2 expression in the adrenal gland and hypertension, a connection that aligns with the pivotal role of tissue-specific voltage-gated L-type calcium channel (LTCC) isoforms in aldosterone biosynthesis." (PMID 39011893, 2024).
myocardial infarction (4 papers, 2017 to 2021). Gross necrosis of the myocardium, as a result of interruption of the blood supply to the area, as in coronary thrombosis. "Jph2 gene therapy in mice with HF was shown to normalize RyR2-induced calcium release, while β-adrenergic receptor blocker treatment improved TT integrity and Jph2 expression in mice after myocardial infarction." (PMID 31810440, 2019). "A study based on a tag-based digital gene expression profiling (DGE) system showed that the mechanism of ventricular remodeling induced by myocardial infarction by BYHWD treatment may be closely related to transforming growth factor beta receptor-1, junctophilin-2, and monocyte." (PMID 34422208, 2021).
Arrhythmia (3 papers, 2019 to 2022). Any cardiac rhythm other than the normal sinus rhythm. "Alterations in JPH2 expression levels can also lead to cardiac arrhythmias, which are, by definition, abnormal rhythms of the heart." (PMID 35001666, 2022).
dementia (3 papers, 2019 to 2022). Loss of intellectual abilities interfering with an individual's social and occupational functions. "In this stratum, enrichment analysis of RRA cortex candidates showed an over-representation of genes involved in cardiac development and function (DLG1, JPH2 or MEF2C among others), supporting a cardiovascular etiology of dementia in this stratum." (PMID 33846280, 2021).
infarction (2 papers, 2017 to 2025). A localised pathological necrosis of tissue resulting from obstruction of the blood supply usually by a thrombus, an embolus, or vascular torsion. "Recent data from our laboratory showed further evidence of pairing of JPH2 expression and t-tubule organization across failing, post-infarction hearts, with the most marked loss of JPH2 and t-tubules observed in regions neighboring the infarct [63•]." (PMID 28447290, 2017).
myocardial ischemia (2 papers, 2020 to 2021). A disorder of cardiac function caused by insufficient blood flow to the muscle tissue of the heart. "Schulz and colleagues showed that MMP-2 is activated and thereby degrades myocardial contractile proteins such as myosin light chain, titin and troponins, as well as sarcoplasmic/ endoplasmic reticulum Ca2+ ATPase 2a (SERCA2a) and junctophilin-2 during myocardial ischemia/reperfusion injury." (PMID 32977437, 2020).
endometrial stromal sarcoma (1 paper, 2020). "JPH2 may serve as a marker for UPS, as it was previously reported to be overexpressed in leiomyosarcomas compared to an endometrial stromal sarcoma." (PMID 32652895, 2020).
familial cardiomyopathies (1 paper, 2024). "In this study, we performed unbiased lipidomic profiling of the hearts from two mouse models of distinct familial cardiomyopathies (HCM and DCM) caused by variants in the same JPH2 gene." (PMID 38438248, 2024).
gastric cancer (1 paper, 2021). A primary or metastatic malignant neoplasm involving the stomach. "JPH2 was among 10 individual genes of a DNA-methylation signature associated with overall survival of gastric cancer patients: in contrast to the JPH1 observations of the present study, higher JPH2-methylation (gene-downregulation) was associated with longer survival." (PMID 36046118, 2021).
metabolic syndrome (1 paper, 2024). A cluster of metabolic risk factors for CARDIOVASCULAR DISEASES and TYPE 2 DIABETES MELLITUS. "Although JPH2 dysfunction has not been linked to TG synthesis, one GWAS in females with early menarche and metabolic syndrome identified an SNP near the JPH2 gene locus, which potentially regulates its expression levels." (PMID 38438248, 2024).
systolic heart failure (1 paper, 2018). Heart failure caused by abnormal myocardial contraction during systole leading to defective cardiac emptying. "Mice with acute conditional cardiac specific knockdown of JPH2 have a high incidence of mortality with a rapid development of systolic heart failure." (PMID 30235249, 2018). "We identified 20 individuals affected with HCM with or without systolic heart failure and conduction abnormalities in the nine Finnish families with JPH2 p.(Thr161Lys) variant." (PMID 30235249, 2018).
thyroid deficiency (1 paper, 2024). "The STORM images support the observation that the majority of Jph2 align with T-tubules along z-lines in normal cells, and that this arrangement is disrupted in thyroid deficiency." (PMID 39365674, 2024).
cardiac disease (12 papers, 2014 to 2025). "T-tubule remodelling in cardiac diseases is associated with downregulation of JPH2 expression suggesting that JPH2 plays a crucial role in T-tubule stability." (PMID 32053184, 2021). "Jph2 functions primarily as a structural protein spanning T-tubule membranes and jSR at dyad structures involved in EC coupling, and it has been proposed as a druggable target in ameliorating deficiencies of cardiac function in aging and heart disease." (PMID 39365674, 2024). "Impaired JPH2 function and expression are associated with cardiac diseases." (PMID 31591206, 2019). "To characterize ethnicity-dependent genetic variability in JPH2 and to identify homozygous JPH2 variants associated with cardiac disease, we identified variants in JPH2 in a worldwide control cohort (gnomAD) and 2 similar cohorts from the Greater Middle East (GME Variome, Iranome)." (PMID 31227780, 2019). "In addition, we did extensive review of the literature and databases about JPH2 variation in association with cardiac disease." (PMID 30235249, 2018). "We implicated a similar mechanism in the degradation of the key SER-PM membrane tethering protein Junctophilin-2 (JPH2) in other cardiac disease." (PMID 39446877, 2024). "In fact, JPH2 downregulation is a common corollary of TAT remodeling in heart disease." (PMID 39804820, 2025). "Two mechanisms have been suggested to explain JPH2 downregulation in cardiac diseases." (PMID 35454077, 2022). "ARP-100 was used as MMP-2 specific inhibitor already in other studies on heart disease: in isolated hearts, ARP-100 reduced ischemia-reperfusion injury via protection against junctophilin 2 or SERCA (Sarcoplasmic reticulum calcium ATPase) degradation." (PMID 33400052, 2021). "During long-term pressure overload where Jph2 expression is retained and t-tubules are better preserved, the transgenic expression of Mg29 has no additional effect on t-tubule structure and cardiac disease progression." (PMID 28706255, 2017).
tumor (3 papers, 2020 to 2025). "Conversely, the genes downregulated in the MYB-expressing epithelial clusters were predominantly tumor-suppressive transcriptional signatures, including OCM, IER2, JPH2, RYR3, MYH11and B3GALT1." (PMID 40950184, 2025). "JPH2 and WISP2 proteins were both confirmed to be expressed in primary MUPS‐1 tissue and tumor cells." (PMID 32652895, 2020).
cardiovascular diseases (1 paper, 2021). "It has been suggested that this migration might disrupt the binding of JPH2 to T-tubules and cause the remodelling of T-tubules observed in cardiovascular diseases." (PMID 32053184, 2021).
JPH2 also shares sentences with these, for which no sentence is quoted: type 2 diabetes (2 papers); cancer (1); channelopathies (1); chronic heart failure (1); Ebstein anomaly (1); Huntington disease (1); idiopathic dilated cardiomyopathy (1); ischemic heart disease (1); ischemic stroke (1); leiomyosarcoma (1); long QT syndrome (1); myocarditis (1); myopathies (1); peripheral neuropathy (1); prostate carcinoma (1); pulmonary edema (1); pulmonary hypertension (1); thyroid (1).